SCDAL (stem cell derived angiogenic lncRNA)
Synonyms: AC103746.1
Gene: Long non-coding RNA gene on chromosome 15 (96,341,226 to 96,345,651, forward strand). Ensembl gene ENSG00000275322.
Diseases named in the same sentence as SCDAL in open-access papers:
SCDAL is named in the same sentence as 3 diseases in open-access papers, as found by Europe PMC text mining. Sharing a sentence is not in itself a finding about the gene and the disease. The quoted sentences say what the papers report.
tumor (1 paper, 2021). "The nearby protein‐coding gene of SCDAL is the nuclear receptor subfamily 2 group F member 2 (NR2F2, also known as COUP‐TFII) gene, which serves as a known regulator in tumor angiogenesis." (PMID 34319658, 2021).
SCDAL also shares sentences with these, for which no sentence is quoted: infarction (1 paper); liver cancer (1).